LINC00467 (long independently transcribed non-coding RNA 467)
Diseases named in the same sentence as LINC00467 in open-access papers (continued):
Sharing a sentence is not in itself a finding about the gene and the disease.
tumor (18 papers, 2014 to 2023). "In addition, several studies have confirmed that high expression of LINC00467 is associated with poor prognosis in various tumor types." (PMID 35719391, 2022). "Increased expression of LINC00467 was positively associated with tumour size and vascular invasion." (PMID 32125766, 2020). "LINC00467 confirmed as a crucial role to regulate tumor cells proliferation, invasion, migration, apoptosis and other aspects." (PMID 36203193, 2022). "LINC00467 often functions as a potential oncogene and shows great promise in the field of tumor exploration and treatment." (PMID 36203193, 2022). "LINC00467 overexpression significantly increased the number of tumor cells that invaded the subsurface of the Transwell chamber." (PMID 34362879, 2021). "In consistent with the results in vitro, LINC00467-overexpressing-MCF-7 cells formed clearly larger tumors than MCF-7-vector cells did, tumor growth curve showed forced expression of LINC00467 led to a significantly faster growth rate." (PMID 33996559, 2021). "Next, we assessed the independent prognostic value of LINC00467 copy number alterations in terms of tumor metastasis and overall survival." (PMID 35095769, 2021). "In contrast, LINC00467 silencing significantly decreased the number of tumor cells that invaded the subsurface of the Transwell chamber." (PMID 34362879, 2021). "To further investigate the role of LINC00467 in tumor immune response, we analyzed the correlation between LINC00467 DNA copy alterations and the infiltration of three immune cell types using the TIMER algorithm." (PMID 35095769, 2021). "LINC00467 has a possible role in the tumor microenvironment and immune evasion." (PMID 36229833, 2022). "In addition, the experimental results of GC liver metastasis model in nude mice induced by injection of OCUM-1 cells via tail vein (figure (5f-g)) exhibited that knockdown of LINC00467 clearly reduced the tumor nodules in liver tissues." (PMID 35549646, 2022). "In addition, LINC00467 is found to have the potential to increase tumor cell resistance to multiple chemotherapeutic agents." (PMID 36203193, 2022). "Taken together, these results suggested that LINC00467 could enhance polarization toward the M2 phenotype and promote the tumor-enhancing role of these M2 macrophages." (PMID 34094954, 2021). "Based on these results, we speculated that LINC00467 might be a negative regulator of anti-tumor immunity, which promoted tumor progression by inhibiting the infiltration of immune cells." (PMID 34956437, 2021). "Collectively, LINC00467 might possess tumor-promoting potential in GC." (PMID 35549646, 2022). "In addition, numerous studies of different tumor types have assessed the prognosis of patients with high or low LINC00467 expression level and its association with prognostic features such as TNM (Tumor, Node, Metastasis) staging, cell differentiation, disease-free survival, and overall survival." (PMID 35719391, 2022). "In addition to being upregulated in normal human testis and kidney tissues, recent studies have confirmed that LINC00467 is overexpressed in various types of human tumor tissues and plays an important role in regulating gene transcription, tumor initiation, and progression." (PMID 35719391, 2022). "The data suggest that linc00467 may play a role in tumourigenesis through reducing DKK1 expression, leading to enhanced tumour cell viability, and that N-Myc-mediated suppression of linc00467 gene transcription counterintuitively blocks N-Myc-mediated cell survival." (PMID 24586304, 2014). "Given that better stability is an essential prerequisite for tumor biomarkers, we sought to assess the stability of LINC00265, LINC00467, UCA1, and SNHG1 in the isolated plasma exosomes." (PMID 36276083, 2022). "There was a substantial relationship between the highly expressed LINC00467 and the clinicopathological characteristics, including tumor size, TNM stage, tumor grade and distance metastasis." (PMID 36203193, 2022).
tumor (continued). "According to our findings, LINC00467 expression is upregulated in CRC, which could lead to tumor progression and poor prognosis in patients with CRC." (PMID 35587748, 2022).
cancer (11 papers, 2020 to 2023). A tumor composed of atypical neoplastic, often pleomorphic cells that invade other tissues. "Except for functioning as a ceRNA in the underlying mechanisms of various human cancers, LINC00467 can also play different biological roles by interacting with certain proteins, regulating classical signaling pathways, or encoding micro peptides." (PMID 35719391, 2022). "As a whole, high expression of LINC00467 has been significantly associated with cancer prognosis but applied to clinical treatment are still a long way to explore on account of whether all tumors high expression levels of LINC00467 are ideal targets for diagnosis and therapy remains unknown." (PMID 36203193, 2022). "In this review, we reported on the expression and molecular mechanisms of LINC00467 in various cancers." (PMID 36203193, 2022). "Further studies have shown up-regulation of LINC00467 in different cancer including those originated from brain, gastrointestinal tract, lung and breast." (PMID 36229833, 2022). "Expression assays of LINC00467 particularly in biofluids such as serum and urine would pave the way for establishment of non-invasive methods for cancer diagnosis." (PMID 36229833, 2022). "In this review, we comprehensively summarize the different functional roles of the newly found LINC00467 in the progression of various cancers." (PMID 35719391, 2022). "In the following sections, we elaborate on the functional roles and molecular mechanism of LINC00467 in various cancers." (PMID 35719391, 2022). "We first analyzed LINC00467 expression across four different types of putative copy number alterations from Genomic Identification of Significant Targets in Cancer (GISTIC)." (PMID 35095769, 2021). "Previous studies have demonstrated that LINC00467 was upregulated in various types of malignant tumors, which contributed to tumorigenesis through different kinds of pathways." (PMID 32226508, 2020). "Previous research have identified the vital function of LINC00467 in several cancers." (PMID 36987414, 2023). "Through this regulatory pattern, LINC00467 could participate in the initiation and development of cancers." (PMID 35719391, 2022). "So, whether LINC00467 can act as an oncogene biomarker in wide range of cancer types is still uncertain." (PMID 36203193, 2022). "Moreover, several studies have assessed functional roles of LINC00467 in xenograft models of cancers." (PMID 36229833, 2022). "Linc00467 was significantly overexpressed in several cancers." (PMID 34713767, 2021). "Then researchers used RNA pull‐down and RIP assays further to confirm that LINC00467 could bind with IGF2BP3 to promote the TRAF5, promoting cell proliferation and metastasis in HCC.LINC00467 not only can bind proteins come into play, but also can sponge with mRNA to regulate cancer development." (PMID 36203193, 2022). "Furthermore, we analysed the RNA-seq data obtained from the Cancer Cell Line Encyclopedia (CCLE) database and found that LINC00467 was overexpressed in PC cell lines compared with other cancer cell lines." (PMID 34094954, 2021).
digestive system tumors (1 paper, 2021). "Regarding research of linc00467 in digestive system tumors, besides CRC, most of them focused on HCC." (PMID 34713767, 2021).
LINC00467 also shares sentences with these, for which no sentence is quoted: cervical cancer (2 papers); liver cancer (2); testicular germ cell tumor (2); colorectal adenocarcinoma (1); glioblastoma (1); leukaemia (1); oligospermia (1); rectal cancer (1).